CXCR4 (C-X-C motif chemokine receptor 4)
Diseases named in the same sentence as CXCR4 in open-access papers (continued):
Sharing a sentence is not in itself a finding about the gene and the disease.
cancer (continued). "In this review, we summarize the current knowledge on the relevance of CXCR4 mutations in cancer biology, focusing on its importance as predictors of clinical presentation and response to therapy." (PMID 32260318, 2020). "More recently, CXCR4 was found upregulated in cancer cells expressing CD24, a cell surface protein associated with adverse prognosis of CCA, together with p-ERK1/2." (PMID 32784743, 2020). "CXCR4 mediates cancer cells metastasis to bone and plays a causal role in the formation of osteolytic lesions." (PMID 32226538, 2020). "In all cases, the activation of CXCR4 in stem and/or cancer stem cells is linked to the acquisition of a migratory cell phenotype and/or metastatic ability." (PMID 33260962, 2020). "Dysregulation of CXCL12/CXCR4 signaling is associated with numerous pathological conditions, including various types of cancers, chronic inflammatory diseases, cardiovascular diseases, and immunodeficiencies." (PMID 32867358, 2020). "C-X-C motif chemokine 12 (CXCL12), the substrate of DPP-4, and its receptor CXCR4 have been associated with the biology of cancer, such as tumor proliferation, survival, invasion and angiogenesis." (PMID 31991851, 2020). "Several studies suggested that the SDF-1α/CXCR4 axis is associated with several biological processes, such as immune response, hematopoiesis, cardiovascular system organogenesis, and cancer progression." (PMID 32344892, 2020). "Collectively, these findings revealed that in response to CXCL12/CXCR4 activation, miR-133a-3p was repressed and implicated with cancer cell motility by upregulating RhoA through direct binding to RhoA 3’UTR." (PMID 30678736, 2019). "Other new exciting theranostic applications include, among many others, C-X-C motif chemokine receptor 4, as well as cancer-associated fibroblasts." (PMID 31718092, 2019). "Treatment with a CXCR4 antagonist was able to reduce metastasis in endometrial cancer (induced by cancer-associated fibroblasts)." (PMID 31263976, 2019). "A recent, relatively large-scale polymorphism analysis (3684 cancer patients and 5114 healthy controls) suggested an association between high CXCR4 expression and increased risk of cancer." (PMID 30791675, 2019). "β-catenin, a key factor in Wnt/β-catenin pathway which plays important role in the metastasis of cancers, was associated with CXCR4 activation and was also reported to influence EMT signaling pathway." (PMID 31275425, 2019). "Activation of CXCL12/CXCR4 axis has been found to be associated with invasion and metastasis in many cancers." (PMID 30678736, 2019). "The results of this study suggest that hypoxia-induced EMT and cancer stemness acquisition is associated with CXCR4 activation by its aberrant promoter demethylation." (PMID 30760238, 2019). "CXCL12 and its specifc receptors CXCR4 have been shown to be associated with the growth and metastasis of a variety of malignant tumors." (PMID 31500630, 2019). "The CXCR4 pathway has been implicated in many types of cancer and enhances cell proliferation, increases cell survival, and enhances invasion and metastasis." (PMID 30642351, 2019). "CXCR4 is the most common chemokine receptor overexpressed in human cancers and is implicated in over 25 different types of cancers." (PMID 30800123, 2019). "Increased levels of CXCR4/CXCL12 have been found in many types of cancer, including BC, and have been associated with metastasis and poor prognosis." (PMID 29849822, 2018). "GPCRs such as CXCR4, LPAR, PAR1, LGR5, and S1PR are up-regulated in many advanced cancers and induce invasion and metastasis, while CXCR4, CXCR1/2 and LGR5 have been linked to TIC-like phenotypes." (PMID 29255247, 2018).
cancer (continued). "The p65 and p50 NF-κB subunits were found to bind directly to the CXCR4 promoter and initiate transcription, and increased CXCR4 cell surface expression was also associated with cancer cell metastasis." (PMID 30060453, 2018). "Overall, expression of CXCR4 is a poor prognostic indicator that is associated with an increase in many of the processes that are associated with cancer progression including cell migration and metastasis." (PMID 29098360, 2018). "Among these interactions, association between the C–X–C motif chemokine receptor 4 (CXCR4) and its ligand, stromal-derived factor 1, was demonstrated to regulate pro-metastatic functions of cells from several cancer types, including ovarian." (PMID 30445726, 2018). "The CXCR4/CXCL12 axis has been extensively associated with different types of cancer correlating with higher aggressiveness and metastasis." (PMID 29920526, 2018). "CXCL12 and its receptor CXCR4 were implicated in cancer cell migration, invasion, and metastasis through formation of chemotactic gradients." (PMID 29596520, 2018). "CXCL12 and its specific receptors CXCR4 have been shown to be associated with the growth and metastasis of a variety of malignant tumors." (PMID 29305742, 2018). "To date, an increasing number of pain studies demonstrate that CXCR4 is associated with nerve injury-induced neuropathic pain, cancer pain, ischemia-reperfusion-induced pain, diabetic neuropathic pain, and opioid tolerance at the DRG or spinal tissues." (PMID 29386025, 2018). "In clear cell renal carcinoma, loss of PRC2-dependent H3K27me3 in cancer cells activates HIF-driven chemokine (C-X-C motif) receptor 4 (CXCR4) expression in support of chemotactic cell invasion, leading to cancer metastasis." (PMID 29556394, 2018). "CXCR4 has been heavily linked to an increasingly invasive phenotype in a variety of cancers types; however, many of the studies have looked at CXCR4 invasion in only a 2D setting." (PMID 29959873, 2018). "Obermajer and colleagues showed that PGE-2 attracts MDSC into ascites of OvCa patients by inducing expression of functional CXCR4 in cancer-associated MDSCs, and plays a role in the production of its ligand CXCL12." (PMID 29854318, 2018). "Several pathways have been associated with CXCR4 in cancer cells, such as Erk/p38 and PI3K/Akt/NFκB, whereas CXCR4 inhibition deactivated Akt without Erk revealing cell context-specific pathway regulation." (PMID 28067275, 2017). "Chemokine CXCL12 gradients drive chemotaxis in a CXCR4-dependent mechanism and have been implicated in cancer metastasis." (PMID 29117251, 2017). "Lastly, several isoforms of CXCR4 have been identified in cancer cell lines, including alternate splice variants." (PMID 28299514, 2017). "In recent years, research has shown an association between CXCL12/CXCR4 signalling and cancer progression." (PMID 29225688, 2017). "Elevated CXCR4 expression levels have been associated with cancer metastasis and worse prognosis, both in hematological disorders and solid tumor cancers." (PMID 28945785, 2017). "The activation of CXCL12/CXCR4 axis is associated with potential progression of cancer, such as invasion, metastasis and chemoresistance." (PMID 28176874, 2017). "In general, our results first indicated that the rs2228014 polymorphism in CXCR4 gene is correlated with an increased risk of cancer, especially among Asian ethnicity." (PMID 27930510, 2016). "First, this research shed lights on the relationship of a synonymous polymorphism in CXCR4 gene and the increased susceptibility to human cancers, especially in Asian population." (PMID 27930510, 2016). "Previous epidemiological studies have reported the relationship between CXC motif chemokine receptor 4 (CXCR4) synonymous polymorphism (rs2228014), and risk of cancer, but the results remained conflicting and controversial." (PMID 27930510, 2016).
cancer (continued). "Overexpression of CXCR4 has been linked to cancer proliferation, cell migration, and tissue-specific homing of cancer cells as well as resistance to conventional and targeted therapies." (PMID 27112767, 2016). "Peroxisome Proliferator-Activated Receptor (PPAR) γ, a member of the nuclear receptor superfamily, has been found to downregulate CXCR4 gene expression in different cancer cells, however the molecular mechanism underlying this effect is not fully understood." (PMID 27556298, 2016). "As a whole, for CXCR4 rs2228014 polymorphism association, the carriers of TT genotype held higher cancer risk than carriers of CT/CC genotype, especially in Asian ethnicity." (PMID 27930510, 2016). "At present, it is well accepted that CXCR4 over-expression is a risk factor of short survivals in certain types of cancer." (PMID 25669980, 2015). "CXCR4 genetic polymorphisms, as well as their expression level, have been associated with cancer development and prognosis." (PMID 26576337, 2015). "In current meta-analysis, we revealed that CXCR4 over-expression were generally associated with poorer survival in most cancer." (PMID 25669980, 2015). "In cancer cells, CXCR4 expression can be caused by hypoxia, NF-κB activation, and ubiquitination inhibition." (PMID 25704881, 2015). "The G-protein coupled chemokine (C-X-C motif) receptor CXCR4 is linked to cancer, HIV, and WHIM (Warts, Hypogammaglobulinemia, Infections, and Myelokathexis) syndrome." (PMID 25514788, 2014). "Its expression is strongly associated with progression in several cancers, e.g., ovarian, including through promoting the proliferation and migration of malignant cells expressing its receptor CXCR4." (PMID 24961933, 2014). "Although traditionally implicated in organ-directed metastasis, CXCR4 is a chemokine receptor that has been linked to cancer progression." (PMID 25165728, 2014). "The high expression of CXCR4 has been often associated with an invasive and migratory phenotype of cancer cells." (PMID 25237365, 2014). "CXCR4 expression is well known to be increased in many cancers, including GBM, and is associated with poor prognosis." (PMID 25238146, 2014). "The chemokine SDF-1α and its unique receptor CXCR4 have been implicated in organ-specific metastases of many cancers." (PMID 24618817, 2014). "We found that silencing of RTVP-1 decreased the expression of CXCR4 which has been associated with cancer stem cell characteristics in various types of tumors." (PMID 23714687, 2013). "The chemokine CXCL12/SDF-1 and its receptor, CXCR4, have been implicated in invasion, survival, and proliferation of carcinoma cells." (PMID 24363762, 2013). "The inhibitory effect of AMP on PC-3 cell migration and invasion was associated with downregulation of CXCR4 protein level, an important biomarker for cancer cell invasion and metastasis." (PMID 22693649, 2012). "CXCR4 is the most common chemokine receptor expressed by cancer cells, and has been thoroughly implicated in metastasis." (PMID 21672222, 2011). "One such molecular avenue is chemokine receptor CXCR4, a seven transmembrane G protein-coupled receptor that has been implicated in the invasion and metastasis of several cancers, including breast." (PMID 22295222, 2011). "In a murine model using nude mice and injection of cancer cells into tail vein, CXCR4 expression was associated with a dramatic increase in liver and lung metastases." (PMID 24212636, 2011). "TGF-β derived from cancer-associated fibroblasts upregulates CXCR4 in initiated prostatic epithelial cells, and expression of CXCR4 correlates with lymph node metastasis in multiple human tumors." (PMID 20352126, 2010). "In multivariable analysis, cancer risk was reduced in women with CXCR4-tropic HIV (adjusted OR = 0.10, 95% CI 0.002–0.84) and with menopause (adjusted OR = 0.08, 95% CI 0.001–0.83)." (PMID 21179547, 2010). "CXCR4 is overexpressed in precancerous/malignant pancreatic lesions and cancer stem cells, and implicated in its pathogenesis." (PMID 21045835, 2010).
cancer (continued). "In ourrenal cell carcinoma patients, a strong CXCR4 expression wassignificantly associated as well with progressed cancer as indicated by theT-status as with dedifferentiation." (PMID 19266088, 2008). "High CXCR4 expression by cancer cells predisposesto aggressive spread and metastasis and ultimately to poor patientoutcomes." (PMID 18779872, 2008). "The CXCL12/CXCR4 axis is involved in multiple critical processes, including cell proliferation, survival, migration, invasion and metastasis, and is associated with more than 20 different types of cancer." (PMID 40909292, 2025). "This is because overexpression of CXCR4, compared to CXCR4− tumors, is linked to poorer outcomes in cancer patients, including an increase in resistance to chemotherapy, higher risk of recurrence, greater metastasis burden, and shorter progression-free and overall survival." (PMID 40307933, 2025). "Studies in human cancers of neuronal origin—derived from tissues that physiologically express Gγ4—have linked Gγ4 overexpression with inhibition of CXCR4-driven chemotaxis, suggesting that similar mechanisms may enforce GC positioning in Tfh." (PMID 41427421, 2025). "On the other hand, CXCR4 showed a strong association with poor survival (HR = 1.38, 95% CI: 1.27–1.49), which is consistent with numerous studies, including, that have implicated CXCR4 in metastasis and poor prognosis across various cancers." (PMID 41024311, 2025). "Indeed, the CXCL12/CXCR4 signaling pathway is well established for its role in metastasis, and CXCR4 overexpression has been associated with cancer cell proliferation, apoptosis resistance, and local invasion." (PMID 40362664, 2025). "In contrast, ACKR3 expression together with CXCR4 is associated with cancer promoting effects." (PMID 41258098, 2025). "Furthermore, it was found that CXCR4-expressing TCSCs follow a chemokine gradient binding to stromal cell-derived factor-1 (SDF-1/CXCL12) released by cancer-associated fibroblasts (CAFs), which increases TCSCs invasiveness and promotes TC metastasis." (PMID 39776907, 2024). "High CXCL12/CXCR4 may be predictive of poor prognosis in many cancer types as it is associated with higher stage and metastasis and lower survival." (PMID 38612911, 2024). "In addition, HER2-mutant cancers are associated with increased expression of the chemokine receptor C-X-C chemokine receptor type 4 (CXCR4)." (PMID 39012378, 2024). "In sum, CXCR4 expression is associated with worse survival and is overexpressed in many cancers." (PMID 38612911, 2024). "CXCR4 overexpression is associated with poor prognosis in many types of cancer." (PMID 37371036, 2023). "In their study, they found that lidocaine, in clinical concentrations, could block through CXCR4 cell migration, causing a significant reduction in cancer cell motility and wound assay scratch." (PMID 36661535, 2023). "Moreover, mutations or deletions within the IDRs of CXCR4 have been associated with various diseases, including cancer and HIV infection." (PMID 36992255, 2023). "The strict interaction between cancer cells and TME alters and damages the stromal structure leading to the release of signal proteins such as SDF-1 (CXCL12) and its receptor called CXCR4; the overexpression of these molecules is associated with cancer progression." (PMID 37627054, 2023). "Elevated levels of CXCR4 are associated with cancer aggressiveness and survival." (PMID 36882818, 2023). "The potential advancement of cancer is associated with the stimulation of the CXCR4/CXCL12 axis." (PMID 37375460, 2023). "The CXCL12/CXCR4 cascade has been identified as a vital component in guiding embryological migration of primordial germ cells, and is implicated in the predisposition of testicular germ cells to cancer." (PMID 36614308, 2023). "CXCR4 overexpression in primary cancers is associated with poor prognosis." (PMID 35145271, 2022). "CXCL12/CXCR4 axis had been proved to be associated with the progression and therapy of cancers." (PMID 36419891, 2022).
cancer (continued). "CXCR4 signaling can prolong the lifespan of stem cells and increase the potential for DNA damage and mutations, thus transforming these cells into cancer stem cells (CSCs), ultimately promoting the progression of cancer." (PMID 35893797, 2022). "CXCR4 has been implicated in the chemotactic migration of cancer cells." (PMID 34121134, 2021). "Moreover, a previous study has reported that CXCR4 is associated with gefitinib resistance in cancer." (PMID 34555268, 2021). "Additionally, the level of CXCR4 was inextricably linked to the T stage (P = 2.4e-06) and the stage of cancer (P = 0.0036)." (PMID 34568309, 2021). "By a combination of all these properties, T22 ensures the architectonic stability of the protein material in the bloodstream and allows a selective intracellular accumulation of T22-empowered protein-only nanoparticles and associated drugs into CXCR4-overexpressing cancer stem cells." (PMID 34834337, 2021). "CXCR4 was elevated in GC and was closely associated with cancer progression and metastasis." (PMID 34113647, 2021). "Furthermore, there is a strong association between CXCR4 overexpression and histological cancer grade in menopausal and TNBC patients." (PMID 34198652, 2021). "It was revealed that CXCR4 is associated with more than 23 types of cancers." (PMID 31787895, 2019). "Furthermore, we also cannot exclude biologic processes of CXCR4 underlying cancer and the influence of anticancer therapies or the hormone response of immune-modulatory drugs." (PMID 28932900, 2018). "Indeed, the over-expression of CXCR4 has been linked to over 20 different types of cancer and is associated with advanced metastatic disease and a poor clinical outcome." (PMID 29682200, 2018). "It remains unknown, however, if interstitial flow directly stimulates cancer cell invasion in vivo and if CXCR4 signaling is similarly implicated." (PMID 30451884, 2018). "A similar therapeutic approach could be implemented for metastasis control in a variety of cancer types in which CXCR4+ MetSCs associate with poor prognosis." (PMID 30190334, 2018). "Moreover, CXCR4 overexpression has previously been linked to increased colony formation in other cancer types." (PMID 29959873, 2018). "Moreover, studies have implicated CXCR4 over-expression to cancer metastasis and are an indicator of poor prognosis and overall patient survival." (PMID 30564115, 2018). "The serotonin receptor HTR2A is linked to CXCR4, suggesting that serotonin released from reactive astrocytes might affect CXCR4+ metastatic cancer cells through this receptor." (PMID 28210624, 2017). "However, the underlying mechanisms of CXCL12/CXCR4 axis and cancer progression have been poorly explored." (PMID 28176874, 2017). "Moreover, expression of CXCR4 on cancer cells was associated with cancer stem cell phenotype and treatment resistance." (PMID 26896000, 2016). "This further supports the hypothesis that dysfunction of the CXCL12/CXCR4 signaling pathway contribute to the pathogenesis of HPV-associated cancer." (PMID 27918748, 2016). "The outcomes of the present meta-analysis demonstrate that the CXCR4 gene rs2228014 polymorphism might be a potential detecting index for the risk of cancer in the future." (PMID 27930510, 2016). "In conclusion, CXCR4 over-expression is associated with poor prognosis in cancer." (PMID 25669980, 2015). "The CXCL12/CXCR4/CXCR7 signaling axis is highly implicated in metastasis of many cancers." (PMID 25909600, 2015). "Additionally, over-expression of CXCR4 in cancer specimens is associated with chemotaxis, invasion, angiogenesis and proliferation independent of their specific histological findings." (PMID 25669980, 2015). "CXCR4 expression has been linked with the malignancy of over 20different cancers." (PMID 24594697, 2014). "Interestingly, our data also demonstrates that epigenetic silencing of CXCR4 in CC cell lines leads to loss of cell adhesion, one of the key events in metastases and cancer progression." (PMID 25114911, 2014).